RNU6-1194P (RNA, U6 small nuclear 1194, pseudogene)
Gene: Small nuclear RNA gene on chromosome 3 (282,689 to 282,792, reverse strand). Ensembl gene ENSG00000252017.
Homologues: Orthologues: chimpanzee U6 (99% identical), pig U6 (77% identical). Paralogues in human: RNU6-16P (81% identical), RNU6-310P (81% identical), RNU6-1152P (80% identical), RNU6-35P (80% identical), RNU6-393P (80% identical), RNU6-39P (80% identical), RNU6-45P (80% identical), RNU6-968P (80% identical), RNU6-1031P (79% identical), RNU6-1083P (79% identical), RNU6-116P (79% identical), RNU6-140P (79% identical), and 1288 more.